TLR4 (toll like receptor 4)
Diseases named in the same sentence as TLR4 in open-access papers (continued):
Sharing a sentence is not in itself a finding about the gene and the disease.
neuropathy (continued). "In the central nervous system, TLR2 and TLR4 are expressed predominantly on glial cells, and for neuropathy, the most relevant expression is on microglia." (PMID 26962463, 2016). "In our experiment, TLR2 and TLR4 were also upregulated in DRG tissue at all of the time points measured after CCI-induced neuropathy." (PMID 26962463, 2016). "Experiments were conducted to evaluate the contribution of TLR2 and TLR4 and their adaptor molecules to neuropathy and their ability to amplify opioid effectiveness." (PMID 26962463, 2016). "Broadly speaking, increased spinal microglial TLR4 activation correlates with both onset of behavioral hypersensitivity in rodent models of neuropathy and following administration of opioids." (PMID 22898544, 2012). "While TLR4 has been studied in various neuropathy models, its role in diabetic neuropathy and its effect on nerve fiber integrity remains unclear." (PMID 41167527, 2025). "However, our data suggest that TLR4 makes a greater contribution to neuropathy development and maintenance, at least in the rat nerve injury-induced neuropathic pain model." (PMID 26962463, 2016). "On the other hand, reduced expression of Caveolin-1 in monocytes was inversely correlated with Toll-like receptor (TLR) 4 levels in T2DM and neuropathy patients suggesting that low CAV1 expression in white cells could aggravate the TLR4-mediated inflammatory cascade." (PMID 32125224, 2020). "The TLR antagonists LPS-RS (TLR2 and TLR4) and LPS-RS Ultrapure (TLR4) similarly diminished pain behavior after CCI, suggesting a greater contribution of TLR4 in neuropathy, at least in the rat nerve injury-induced neuropathic pain model." (PMID 26962463, 2016). "Biochemical analysis revealed time-dependent upregulation of mRNA and/or protein levels of TLR2 and TLR4 and MyD88 and TRIF adaptor molecules, which was paralleled by an increase in IBA-1/CD40-positive cells under neuropathy." (PMID 26962463, 2016). "A higher significant prevalence was detected for neuropathy, lower limb arteriopathy, and MACE in positive A/G TLR4 patients, when compared with those positive for A/A TLR4 genotype." (PMID 24803744, 2014). "In vivo, CAV1 expression in monocytes from diabetic patients decreased, while TLR4 and TNF-α secretion increased and even more significantly in diabetic patients with neuropathy, suggesting, a role of CAV1 in regulating TLR4-mediated inflammatory cascade in T2DM." (PMID 32082483, 2020). "These neuropathy molecules include CGRP(↓), substance P(↓) and BDNF(↑), neuropeptide Y(↑), galanin(↑) via glial activation, which in turn activates the TNFα, MCP-1 and TLR4 pathways." (PMID 21996269, 2011). "Moreover, a highly specific TLR4 antagonist modulated the interleukin expression levels in DRG, restoring the balance between pronociceptive IL-18 and analgesic IL-18BP, and increased the IL-6 level, which in neuropathy is known to have analgesic properties." (PMID 29656686, 2018).
allergic rhinitis (28 papers, 2005 to 2025). Inflammation of the nasal mucous membranes caused by an IgE-mediated response to external allergens. "A recent research found that miR-224-5p overexpression has the potential to inhibit the TLR4/MyD88/NF-κB pathway, thus reducing the ovalbumin-induced allergic rhinitis-associated inflammatory response and thereby limiting allergic rhinitis." (PMID 39421730, 2024). "Research has demonstrated that Toll-like receptor 4 (TLR4) is integral to the pathogenesis of allergic rhinitis, with alterations in its expression and function potentially contributing to the onset and progression of the disease." (PMID 40870825, 2025). "The study involved molecular docking analysis of berberine with five key genes (Alb, Il6, Il1b, Tlr4, and Ptgs2) to validate its potential targets against allergic rhinitis." (PMID 38796469, 2024). "Overexpression of Tlr4 is observed in individuals suffering from persistent allergic rhinitis, contributing to the advancement of allergic inflammation in this condition." (PMID 38796469, 2024). "Saposhnikovia divaricata aqueous extracts and daphnetin (a bioactive coumarin derivate) displayed anti-inflammatory and antiallergic effects in allergic rhinitis (AR) models through modulating TLR4/NF-κB signaling." (PMID 36840208, 2023). "As an anti-inflammatory molecule, miR-146a was shown to attenuate hepatocyte apoptosis and murine allergic rhinitis by downregulating the TLR4/NF-κB pathway." (PMID 33532131, 2021). "For instance, BZYQ decoction inhibited T helper 2 (Th2) responses and promoted interleukin 12 (IL-12) release from macrophages by increasing TLR4 expression in murine allergic rhinitis models." (PMID 31915455, 2019). "Confocal analysis of the inflammatory nasal mucosa in allergic rhinitis revealed a marked downregulation of both TLR4 and TLR9." (PMID 22577387, 2012). "Our finding of a lower TLR4 expression in the nasal mucosa allergic rhinitis is in line with the reported low expression of TLR4 in T cells and the lack of response to LPS in atopic adults." (PMID 22577387, 2012). "A similar post-translational effect has been described in nasal epithelium of patients with allergic rhinitis compared to healthy subjects, while nuclear localisation of TLR4 has been confirmed in bronchial epithelium." (PMID 18034897, 2007). "An up-regulation of TLR2, TLR3 and TLR4 in the nasal mucosa of patients with symptomatic allergic rhinitis supports the idea of a role for TLRs in allergic inflammation." (PMID 16146574, 2005). "Similarly to previously, in the allergic rhinitis model (AR) and in β-lactoglobulin-induced food allergy, miRNA-146a showed anti-inflammatory potential by inhibiting the TLR4/TRAF6/NF-κB pathway." (PMID 41294623, 2025). "TLR-4 expression was significantly upregulated in allergic rhinitis patients." (PMID 38045687, 2023). "The present study was designed to quantify mRNA and protein expressions of TLR2, TLR3 and TLR4 in the nasal mucosa of patients with seasonal allergic rhinitis, before and after pollen exposure, and to compare these findings with data derived from healthy volunteers." (PMID 16146574, 2005). "Furthermore, the MCODE plugin was employed to pinpoint 14 genes (Cyba, Nfkbia, Fos, Mpo, Il6, Il1b, Sele, Vcam1, F2, Tlr4, Alb, Egr1, Smad3, and Ptgs2) forming a primary cluster, potentially representing a crucial regulatory network for berberine in treating allergic rhinitis." (PMID 38796469, 2024). "These compounds alleviate allergic rhinitis symptoms by inhibiting inflammatory mediators, oxidative stress, apoptosis, and key signaling pathways such as MAPK/NFκB and TLR4/MyD88/NF-κB." (PMID 39403140, 2024). "The safe and effective use of a stand-alone intranasally administered TLR4 agonist and natural exposure to allergens in individuals who are poly-sensitized to multiple seasonal allergens could change the landscape on AIT options available for allergic rhinitis and other atopic diseases." (PMID 39108263, 2024).
allergic rhinitis (continued). "Therefore, our finding of a lower expression of TLR4 and TLR9 in the nasal mucosal of allergic rhinitis patients may be related to the Th2-type allergic inflammation and to the increased susceptibility to upper respiratory infections usually observed in rhinitis patients." (PMID 22577387, 2012).
chronic kidney disease (28 papers, 2014 to 2026). Impairment of the renal function secondary to chronic kidney damage persisting for three or more months. "The present exploratory case–control analysis sought to elucidate potential associations between the TLR4 rs2149356 polymorphism, end-stage renal disease (ESRD), and periodontal status." (PMID 41002387, 2025). "It have been documented that TLR4 is linked to the pathophysiology of both acute and chronic kidney diseases." (PMID 41168881, 2025). "This study explored the association of the TLR4 rs2149356 polymorphism with periodontal and renal parameters in Egyptian end-stage renal disease (ESRD) patients." (PMID 41002387, 2025). "Among all TLRs, TLR4 has been reported to be implicated in the pathogenesis of acute kidney injury, chronic kidney diseases, and the occurrence of DN." (PMID 29604956, 2018). "Indeed, TLR4 has been implicated in the modulation of kidney fibrosis and the development of chronic kidney disease (CKD) following acute injury." (PMID 27136544, 2016). "Chronic kidney disease induces inflammation by increasing Toll-like receptor-4 (TLR4), cytokine and cathelicidin expression in neutrophils and monocytes." (PMID 39671124, 2024). "We extended our studies of Fstl1 and its receptors Tlr4 and Dip2a in another experimental model of chronic kidney disease: murine UUO." (PMID 34502419, 2021). "In stage 5 predialysis chronic kidney disease (CKD) patients a reduced expression of TLR4 has been observed." (PMID 30228352, 2018). "There is accumulating evidence suggesting that TLR4 aggravates renal dysfunction in acute and chronic kidney diseases." (PMID 28542370, 2017). "Because TLR4 rs11536889 GG patients may exhibit decreased TLR4 expression, our results are consistent with former observations indicating that decreased TLR4 expression in chronic kidney disease patients was associated with attenuated proinflammatory cytokine synthesis during infection." (PMID 24950711, 2014). "Our data indicate that BB intervention inhibits TLR4 in chronic kidney disease, thereby augmenting the anti-inflammatory actions of Nrf2 over the pro-inflammatory actions of NFκB." (PMID 25372283, 2014). "TLR4/NLRP3 signaling has been implicated in fibrogenesis and progression to chronic kidney disease." (PMID 40869248, 2025). "Upon stimulation, activation of TLR4 pathway subsequently activated the NF-κB pathway and triggered NF-κB-dependent inflammatory response, which might ultimately aggravate renal dysfunction in acute and chronic kidney diseases." (PMID 29604956, 2018). "Similarly, in the kidneys, lipid accumulation disrupts podocyte function and induces inflammation through toll-like receptor 4 (TLR4)-NF-κB activation, exacerbating glomerular damage and chronic kidney disease." (PMID 41235339, 2025). "Moreover, whereas TLR2 and TLR4 are over-expressed on monocytes from patients on haemodialysis, the expression of TLR4 has been reported to be reduced on monocytes in patients with chronic kidney disease (CKD) not receiving dialysis." (PMID 30026783, 2018).
lung adenocarcinoma (28 papers, 2013 to 2025). A carcinoma that arises from the lung and is characterized by the presence of malignant glandular epithelial cells. "According to a risk score analysis, the down-regulation of TLR4 in high-risk groups among the ferroptosis-related 15-gene signature suggests a protective role of TLR4 in lung adenocarcinoma." (PMID 39238498, 2024). "The COSMIC database further showed a high proportion of TLR4 non-synonymous mutations in cutaneous melanoma (60/988, 6.1%), lung adenocarcinoma (22/477, 4.6%), stomach adenocarcinoma (26/579, 4.5%) and lung squamous cell carcinoma (17/497, 3.4%)." (PMID 28531216, 2017). "In lung adenocarcinoma, LPS stimulation also caused a remarkable increase in TLR4, MyD88 and p-p65 protein expression, as well as NEAT1 mRNA expression, which could be partially reversed by CLI-095, an inhibitor of TLR4 signaling." (PMID 29788922, 2018). "Our previous study also demonstrated that resistin promotes lung adenocarcinoma metastasis through the TLR4/Src/EGFR/PI3K/NF-κB pathway." (PMID 40002704, 2025). "Resistin leads to lung adenocarcinoma cell migration and invasion through the TLR4/Src/EGFR/PI3K/NF‐κB pathway." (PMID 40040878, 2025). "In lung adenocarcinoma, our previous study demonstrated that resistin promotes metastasis via the TLR4/Src/EGFR/PI3K/NF-κB signaling pathway." (PMID 40002704, 2025). "TLR4 expression was elevated in myeloid dendritic type 1 and type 2 in lung adenocarcinoma, as well as in EREG+DC, IGSF21+DC, and myeloid dendritic type 1 and type 2 in lung squamous cell carcinoma tissues, compared to normal tissues." (PMID 39238498, 2024). "Recently, protective effects of TLR4 have been identified on the outcome for lung adenocarcinoma, which are in good agreement with our signature in EC." (PMID 35911966, 2022). "We found that the IHC expression scores of TLR4 in lung adenocarcinomas (ADCs) and squamous carcinomas (SCCs) were significantly higher than that of MOR (P < 0.001)." (PMID 33628591, 2021). "Resistin can also increase EGFR phosphorylation through the Toll-like receptor 4 (TLR4)/Src pathway and thereby promote lung adenocarcinoma metastasis." (PMID 33313320, 2020). "Upregulation of TLR4 significantly increases the expression of KDM3A in A549 lung adenocarcinoma cells, which subsequently controls Foxp3 transcription." (PMID 32354028, 2020). "In lung adenocarcinoma murine models, immunogenic chemotherapy (oxaliplatin-cyclophosphamide) has been reported to up-regulate toll-like receptor 4 (TLR-4) on tumor-infiltrating Batf3-cDCs, which leads to the recruitment of CTLs and sensitization to iCPIs." (PMID 31555274, 2019). "The data indicate that Galectin-3 and TLR4 expression are abnormally up-regulated in lung adenocarcinoma tissues; Galectin-3 affects lung adenocarcinoma cell proliferation and migration through activating TLR4/NF-κB pathway and NEAT1 expression." (PMID 29788922, 2018). "In lung adenocarcinoma murine models, immunogenic chemotherapy (oxaliplatin-cyclophosphamide) has been reported to up-regulate toll-like receptor 4 (TLR-4) on tumor-infiltrating Batf3-cDCs, which leads to recruitment of CTLs and sensitization to ICIs." (PMID 29970158, 2018). "Galectin-3 and TLR4 expression are abnormally up-regulated in lung adenocarcinoma tissues, and positively correlated with NEAT1 expression." (PMID 29788922, 2018). "Remarkably, an up-regulation of TLR-4 expression was recently demonstrated in human adenocarcinoma of the lung in vivo and TLR-4 expression levels correlated with malignancy." (PMID 28314957, 2017). "This is of particular interest, as an up-regulation of TLR4 expression has been reported recently in human adenocarcinoma of the lung with TLR4 expression levels correlating with malignancy." (PMID 22923191, 2013). "Most importantly, an up-regulation of TLR4 expression was recently demonstrated in human adenocarcinoma of the lung in vivo, and TLR4 expression levels correlated with malignancy." (PMID 22923191, 2013).
lung adenocarcinoma (continued). "Gene mutations observed differ between lung adenocarcinoma and lung squamous cell carcinoma, with KRAS, EGFR, LPHN3, KEAP1, and TLR4 being relatively common in lung adenocarcinoma, whereas BAI3, FBXW7, GRM8, ERBB4, MUC16, and RUNX1T1 are common in lung squamous cell carcinoma." (PMID 39594843, 2024). "Taken together, the activation of TLR4 could suppress lung adenocarcinoma in vivo to some extent, identical to our previous analysis." (PMID 37553698, 2023). "Therefore, in order to verify the function of TLR4, we first chose to compare the TLR4 expression in human lung adenocarcinoma A549 cells and normal human lung fibroblasts HLF cells under in vitro." (PMID 37553698, 2023). "We confirmed that Galectin-3 as a ligand of TLR4 induced TLR4 signaling activation in lung adenocarcinoma cells, thereby activating downstream p65 nucleus translocation, promoting NEAT1 expression, and finally affecting lung adenocarcinoma cell proliferation and migration." (PMID 29788922, 2018). "Galectin-3 reportedly serves as a ligand of TLR4 and promotes TLR4, MyD88 and p-p65 expression; we investigated whether Galectin-3 could modulate lung adenocarcinoma cell proliferation and migration through TLR4/NF-κB/NEAT1." (PMID 29788922, 2018). "Moreover, the mRNA expression and protein levels of Galectin-3 and TLR4 in lung adenocarcinoma samples were much higher than those in normal lung tissues." (PMID 29788922, 2018). "However, LPS-induced TLR4/NF-κB activation has been well studied in cancers; herein, we investigated other possible upstream factors which can activate this key signaling pathway in lung adenocarcinoma." (PMID 29788922, 2018). "Here, we explored the upstream regulatory factors and mechanisms of NEAT1 abnormal overexpression in lung adenocarcinoma, and further suggest a regulatory path formed by Galectin-3, TLR4, NF-κB and NEAT1 that may contribute to the hyperproliferation and migration of lung adenocarcinoma cells." (PMID 29788922, 2018). "Herein, we also observed that Galectin-3 overexpression remarkably induced TLR4 protein expression, as well as lung adenocarcinoma cell proliferation and migration; next, we further investigated whether Galectin-3 exerts its function through downstream NF-κB and NEAT1." (PMID 29788922, 2018). "Bioinformatics analysis revealed that downregulation of TLR4 and TLR8 positively impacts the survival in lung adenocarcinoma (LUAD) and lung squamous cell carcinoma (LUSC)." (PMID 40025339, 2025). "The data indicate that Galectin-3 induces TLR4/NF-κB signaling activation, followed by NEAT1 expression upregulation, and ultimately promotes lung adenocarcinoma cell proliferation and migration." (PMID 29788922, 2018). "Inhibiting Galectin-3-induced TLR4 signaling activation, thus to reduce p65-activated NEAT1 expression might be a promising strategy of suppressing lung adenocarcinoma cell proliferation and migration." (PMID 29788922, 2018). "Galectin-3 and TLR4 were both overexpressed in lung adenocarcinoma tissues, compared to those in non-tumor control." (PMID 29788922, 2018). "As a further confirmation of these data, the mRNA expression of Galectin-3 and TLR4 in lung adenocarcinoma and non-cancerous tissue samples were examined." (PMID 29788922, 2018). "Because of no clear conclusion confirming the specific role in lung adenocarcinoma, TLR4 attracts our attention, which enables to stimulate NLRP3 inflammasomes via enhancing the activation of nuclear factor-κB (NF-κB), releasing more pro-inflammatory cytokines like IL-1β and IL-18." (PMID 37553698, 2023). "Another study has shown that resistin activates Toll-like receptor 4 (TLR4) and engages with the Src pathway which activated the EGFR phosphorylation and increased epithelial-mesenchymal transition (EMT), subsequently inducing the migration and invasion of lung adenocarcinoma." (PMID 33313320, 2020).
lung adenocarcinoma (continued). "The effect of Oxaliplatin combined with Cyclophosphamide (Oxa-Cyt) treatment on tumors relied on TLR4 signaling; Oxa-Cyt treatment led to an increase of TLR4 selectively in DC cells within the tumor stroma and ultimately led to CD8+ T-cell anti-tumor immunity in lung adenocarcinoma mouse models." (PMID 32656079, 2020).